ALB (albumin)
Diseases named in the same sentence as ALB in open-access papers (continued):
Sharing a sentence is not in itself a finding about the gene and the disease.
Hypoalbuminemia (continued). "They recently performed a randomized controlled trial evaluating the effects of exogenous 20% human albumin solution vs saline on the incidence of postoperative AKI in adult patients with hypoalbuminemia (< 40 g/L) undergoing off-pump coronary artery bypass surgery." (PMID 31477030, 2019). "Low albumin levels in cirrhotic patients can drive neutrophil dysfunction; as albumin binds excess endotoxin, elevated endotoxin levels lead to chronic signaling in innate immune cells as a consequence of hypoalbuminemia." (PMID 31627733, 2019). "IL-1β and TNF-α may also contribute to the hypoalbuminaemia and weight loss seen in FIP via decreased albumin production and increased muscle breakdown respectively." (PMID 31835559, 2019). "As the production of BChE and albumin in the liver occur in a coupled fashion, mechanisms leading to a decrease of serum BChE levels might be comparable to those leading to hypoalbuminemia." (PMID 30737542, 2019). "Since total protein measurement by biuret method and plasma protein electrophoresis is the gold standard to obtain accurate plasma albumin in reptiles, falsely increased albumin may mask hypoalbuminemia in leatherbacks." (PMID 31504062, 2019). "About 12% of the patients (N = 704) had hypoalbuminemia (albumin<3.5 g/dL)." (PMID 30637771, 2019). "In particular, patients with hypoalbuminemia may benefit from serum albumin level correction prior to surgery." (PMID 31547129, 2019). "Still, underreporting of complications is a common problem in retrospective studies, but these mistakes might be distributed equally between groups with normal albumin concentrations and hypoalbuminemia." (PMID 31468203, 2019). "In the subgroup analysis, treatment was significantly associated with lower in-hospital mortality rates among those with hypoalbuminemia (albumin < 3.0 mg/dL; adjusted OR, 0.53; 95% CI, 0.30–0.93; p = 0.02) and higher SOFA scores (>10 points; adjusted OR, 0.53; 95% CI, 0.29–0.97; p = 0.03)." (PMID 30654592, 2019). "Hypoalbuminemia might be related to the liver dysfunction, which was evident by elevated liver enzymes, and due to increased albumin glomerular leakage." (PMID 32128099, 2019). "Albumin is synthesized in the liver and has a half-life of approximately 3 weeks, and an albumin concentration less than 3.5 g/dl is generally referred to as hypoalbuminemia." (PMID 31565439, 2019). "In this study, low level of serum albumin level was positively correlated with the low level of 25(OH) D level; indicating that hypoalbuminemia may be one of the potential contributing factor to the low level of 25(OH) D levels." (PMID 31315585, 2019). "A future study could aim to evaluate the role of albumin replacement in the treatment of acute pancreatitis with hypoalbuminemia." (PMID 31068202, 2019). "Moreover, the serum albumin level had a significant inverse correlation with proteinuria and glomerular lesions, two well-known risk factors for DN progression, which might give some explanation for the association between the hypoalbuminemia and renal outcome." (PMID 30911552, 2019). "We defined hypoalbuminemia as a serum level of albumin < 2.6 g/dl." (PMID 29063302, 2018). "However, four dogs (10%) had hypoalbuminemia with a median (range) serum albumin concentration of 12.2 g/L (11-13 g/L)." (PMID 29618371, 2018). "As albumin concentration rises with increasing GA, even in survivors of ELBWIs observed in the present study, setting the precise reference ranges for pathological hypoalbuminemia playing a prognostic role has proved difficult to determine in ELBWIs." (PMID 29438382, 2018). "However, it is worth noting that intravenous albumin was likely administered the most in the case of severe hypoalbuminemia, which remained associated with AKI despite any possible interfering effect of subsequent corrections of serum albumin levels." (PMID 30097635, 2018).
Hypoalbuminemia (continued). "Some groups have shown a decrease of albumin concentration with aging, while others have demonstrated that age is not a cause of hypoalbuminemia." (PMID 29772765, 2018). "The relationship of hypoalbuminemia to postoperative AKI might be attributable to the renoprotective properties of albumin." (PMID 30395651, 2018). "Pretreatment hypoalbuminemia (albumin < 35 g/l) occurred in 174 patients (16.3%)." (PMID 30116261, 2018). "An imbalance between intravascular and extravascular albumin levels may also result in hypoalbuminemia." (PMID 30275523, 2018). "Thirty-seven patients (52.9%) had hypoalbuminemia (ALB < 35 g/L)." (PMID 29506546, 2018). "Combination therapy with furosemide and albumin might be possible for patients with hypoalbuminemia, but evidence to clarify the clinical significance of such combination therapy is lacking, even in patients with liver cirrhosis." (PMID 29063302, 2018). "Additionally, old age, prolonged colistin administration, hypoalbuminemia, low serum albumin level, high Charlson Comorbidity Index, and the presence of septic shock were reported to be related to nephrotoxicity." (PMID 30462703, 2018). "Hypoalbuminemia is common in patients with a low BMI and because of the lipophilic character of fentanyl, the binding of fentanyl to plasma proteins like albumin might be influenced by the plasma concentration of albumin." (PMID 29883454, 2018). "For patients with hypoalbuminemia, the mean level of albumin was 2.2 ± 0.3 (2.1–2.4) g/dl." (PMID 29063302, 2018). "In dogs, cytokine IL6 suppresses albumin synthesis and may be released by neoplastic cells, and this might contribute to the progressive hypoalbuminaemia observed in AL." (PMID 30305106, 2018). "Hypoalbuminemia The baseline albumin values for a total of 14 patients were normal." (PMID 30142174, 2018). "Similarly, concerning the other component influencing TAC, albumin, it has been reported that hypoalbuminemia in trauma patients can be secondary to low synthetic rates, hypercatabolism or vascular efflux, all leading to diminished TAC." (PMID 30308018, 2018). "In most patients, there was hypoalbuminemia, but one patient (3%) had a normal albumin level and thus developed capillary leakage by another unknown mechanism." (PMID 30404164, 2018). "It is justified to use albumin as a resuscitation fluid in patients with hypoalbuminemia." (PMID 29789983, 2018). "Because hypoalbuminemia could affect its interpretation, AG should be corrected for serum albumin level." (PMID 28469150, 2017). "Persistent organ failure developed in 3.5% (15/424) patients with normal albumin, 10.1% (20/198) patients with mild hypoalbuminemia, and 42.3% (33/78) with severe hypoalbuminemia when patients were divided into three groups according to different albumin levels." (PMID 29147647, 2017). "The mean serum albumin concentration was 3.28 ± 0.48 and 72% of the patients had hypoalbuminemia." (PMID 29267516, 2017). "A large, multicenter, randomized study conducted in ICU patients with severe sepsis reported that the correction of hypoalbuminemia by the addition of 20% albumin to crystalloids, as compared with crystalloids alone, had significant benefits on hemodynamics but did not confer a survival benefit." (PMID 28744467, 2017). "The most common findings observed were anemia, leukocytosis, neutropenia, lymphopenia, thrombocytopenia, eosinophilia followed by hyperbilirubinemia, increased level of AST, ALT and ALKP, hypoalbuminemia, hyperglobulinaemia, decrease in albumin and globulin ratio, increase in BUN and creatinine." (PMID 28344412, 2017). "Hemoconcentration due to dehydration especially in AN-BP patients may falsely normalize albumin level, with unmasking of hypoalbuminemia after rehydration." (PMID 28257095, 2017). "Presence of hypoalbuminemia alone in patients with NS (a condition that is caused by the disease) does not justify albumin use." (PMID 28443947, 2017).
Hypoalbuminemia (continued). "It is unknown whether administration of albumin would improve the clinical outcomes of acute pancreatitis with hypoalbuminemia though severe acute pancreatitis has many similarities to sepsis syndrome and septic shock." (PMID 29147647, 2017). "Forty-six per cent of the patients had hypoalbuminaemia (albumin < 2.8 g/dl)." (PMID 28345730, 2017). "Indeed, the risk of PPCs associated with eGFR was attenuated in the fully-adjusted model including serum albumin, suggesting the link between hypoalbuminemia and protein-energy wasting." (PMID 28747700, 2017). "Hypoalbuminemia is a risk factor for AKI and for death after AKI, so serum albumin determinations may be useful to identify patients at increased risk for AKI and for death following AKI." (PMID 28744467, 2017). "Besides these three variables, preoperative hypoalbuminemia (albumin level < 4 g/dL), the highest intraoperative lactate level, and total urine output during surgery were likely to increase the incidence of AKI (P < 0.20)." (PMID 29457099, 2017). "This hypoalbuminaemia is usually corrected by administration of exogenous albumin." (PMID 28800610, 2017). "Many children with BA may have an excessively low albumin level early after surgery, which may be explained by preoperative hypoalbuminemia and surgical stress." (PMID 28690638, 2017). "Therefore, preoperative vitamin K and albumin supplementation to correct coagulation disorders and hypoalbuminemia is valuable for increasing patient tolerance and the surgical success rate and reducing postoperative complications." (PMID 28690638, 2017). "She continued conservative therapy with high dosage for another 30 days, but then she developed severe hypoalbuminemia (serum albumin measuring at 1.9 g/dL while baseline serum albumin was 3.8 g/dL) and peripheral edema that resolved after reducing the dose to 50 mg twice daily." (PMID 28687078, 2017). "However, many studies have demonstrated that the cancer-related systemic inflammatory response has a more significant impact on hypoalbuminemia, which is mainly attributed to the cytokine-induced suppression of albumin synthesis and its increased degradation." (PMID 26966671, 2016). "Low concentrations of serum albumin (hypoalbuminemia) indicates poor nutritional status and low performance status but albumin may also decrease due to many other conditions such as systemic inflammation." (PMID 27632196, 2016). "In agreement with the established increase in OS in chronic kidney disease (CKD) patients, recent studies have shown that apparent hypoalbuminemia is partially due to oxidation of albumin which impairs its quantification by the standard laboratory assay using bromocresol-green (BCG)." (PMID 27453993, 2016). "Larger prospective ABPM studies addressing the relationship between circadian BP rhythm and serum and urinary albumin among hypertensive patients with massive albuminuria or hypoalbuminemia are needed, as are advanced biochemical markers of target organ damage and cardiovascular risk." (PMID 27276394, 2016). "Moreover, hypoalbuminemia was reported as an independent prognostic marker of cancer fatality, and prognostic nutritional index calculated based on serum albumin and lymphocytes was reported as a prognostic marker in stomach cancer patients." (PMID 27863481, 2016). "Patients suffering from hypoalbuminemia (< 36 g/L) had a significantly shorter survival time of 18.0 months (95% CI 12.7–23.2) compared to 31.7 months (95% CI 26.6–36.8) (p < 0.001) for those with normal albumin level (HR 1.8, 95% CI 1.3–2.4, p < 0.001)." (PMID 27632196, 2016). "However, in the postoperative period, owing to the presence of liver disease, hypoalbuminemia (ALB < 25.0 g/L) was observed in 17 patients, which was corrected by infusion of human albumin." (PMID 27843449, 2016). "Moreover, 16.67% patients with hypoalbuminemia suffered from MC while only 2.44% patients suffered from MC in patients with normal albumin (P = 0.002)." (PMID 27684858, 2016).
Hypoalbuminemia (continued). "The majority of patients had normal albumin levels, whereas 38% had hypoalbuminemia (< 36.0 g/L)." (PMID 27632196, 2016). "Hypoalbuminemia, defined as a first serum albumin of less than 3.0 g/dL on the initial patient visit, could be observed in one-fourth to three-fourths of scrub typhus patients." (PMID 27287396, 2016). "Serum albumin levels are commonly used for epidemiological studies, although without knowledge about the oxidative stress of the patients it is impossible to distinguish between true and apparent hypoalbuminemia." (PMID 27453993, 2016). "Because serum albumin concentration was more frequently tested in malnourished or severely ill individuals who were suspected of hypoalbuminemia, this may have led to an inherent selection bias." (PMID 27504458, 2016). "In geriatric patients, hypoalbuminemia may be physiologic, as the aging process islinked with lower levels of serum albumin, that is 20% lower in individuals over 70years old." (PMID 27508908, 2016). "Similarly, 87.8 % were hypoalbuminemic (serum albumin < 30 g/L), 41.5 % had severe hypoalbuminemia defined as serum albumin < 20 g/L." (PMID 27717323, 2016). "We observed that the use of two albumin-related parameters, i.e., the lowest albumin concentration at the critical phase and the degree of hypoalbuminemia, for predicting a diagnosis of pleural effusion and/or ascites may not be conclusive." (PMID 27391122, 2016). "Mild hypoalbuminemia was observed (mean serum albumin − 3g/dl)." (PMID 27413521, 2016). "They further stated that their findings were consistent with the hypothesis that albumin may assist furosemide delivery to its site of action and increase renal blood flow in patients with hypoalbuminemia." (PMID 26457719, 2015). "The ubiquitous occurrence of hypoalbuminemia in critically ill patients is not seen as counterregulation but is based on the albumin loss due to third space losses, plasma dilution or reduced hepatic production (negative acute phase response)." (PMID 25888397, 2015). "Similarly, low BMI, low albumin and low CD4 counts were linked to anemia; while, hypoalbuminemia was associated with low hemoglobin levels and CD4 counts." (PMID 26825478, 2015). "Of the participants assessed, mean serum albumin was 3.95 ± 0.46 g/dL; 12.7 % had hypoalbuminemia." (PMID 26651991, 2015). "Low serum albumin levels predispose these patients to have reduced potential for oxygen radical scavenging, which in turn aggravates the sepsis and then leads back to hypoalbuminemia in a more severe form via decreased albumin synthesis and altered distribution." (PMID 25923115, 2015). "Given that inflammation and hypoalbuminemia are two diagnostic indices for cachexia, the level of albumin in the severe cachectic mice was not surprised significantly lower (p < 0.05, TModerate vs. TSevere) than that in the moderate." (PMID 25797259, 2015). "Therefore, it is possible that Dense Kidney reflects the reabsorption of albumin at the proximal tubule and would be helpful to interpret hypoalbuminemia in NS cases with limited urine protein excretion." (PMID 25859658, 2015). "Hypoalbuminemia may also stimulate the release of an as yet unidentified circulating factor that contributes to elevation in hepatic albumin synthesis." (PMID 25859658, 2015). "Indeed, a positive correlation between serum albumin and BChE activity was observed, despite the fact that 8 patients (20%) with severe hypoalbuminemia (plasma albumin < 20 g/L) received albumin substitution (rs = 0.53, Spearman's rank correlation test)." (PMID 25762852, 2015). "Hypoalbuminemia induces marked albumin and lipoprotein synthesis." (PMID 26640497, 2015). "Main outcome measures are serum albumin levels and prevalence of hypoalbuminemia." (PMID 26651991, 2015). "However, the concentration of serum albumin is often decreased in a great deal of conditions, for example, in major surgery, trauma or infection, and if serum albumin <35 g/L, hypoalbuminemia would be diagnosed." (PMID 26557421, 2015).
Hypoalbuminemia (continued). "In adults, the normal ALB range is 35–50 g/L; levels <35 g/L are termed hypoalbuminemia." (PMID 24718309, 2014). "The meta-analysis of nine prospective controlled trials on correcting hypoalbuminemia in acutely ill patients mentioned earlier suggested that complication rates were reduced in patients who achieved serum albumin concentrations >30 g/l after albumin administration." (PMID 25042164, 2014). "Previous studies have shown hypoalbuminemia to be associated with increased mortality, but have not assessed the predictive power on mortality of low albumin levels in an unselected acutely admitted medical population." (PMID 25148079, 2014). "Furthermore, serum albumin is one of the components of the Child-Pugh Classification and hypoalbuminemia has been reported as an independent poor prognostic factor in patients with HCC." (PMID 23374755, 2013). "Although being speculative, reduced antioxidant effect based on hypoalbuminemia and concomitant change of quality of albumin in advanced stage of PBC might be one of the reasons of hepatocarcinogensis." (PMID 23533384, 2013). "Serum albumin done in 126 (68.5%) patients revealed hypoalbuminaemia in 108 (58.7%) patients." (PMID 24067148, 2013). "Forty five patients (20%) had hypoalbuminaemia (serum albumin less than 3.5 g/L)." (PMID 23590192, 2013). "The patients with hypoalbuminemia were supported with human albumin." (PMID 23782501, 2013). "It is likely that the cause of hypoalbuminemia, rather than albumin levels per se, drives increased morbidity in uremic patients." (PMID 23923025, 2013). "Similarly, the presence of hypoalbuminaemia (albumin < 5 g/dL) was found to confer 1.41 times inferior survival capability." (PMID 23840958, 2013). "Hypoalbuminemia may reflect the incidences of diabetic nephropathy-related proteinuria and suppressed albumin synthesis due to acute illnesses." (PMID 23724053, 2013). "Serum albumin done in 78 patients revealed hypoalbuminaemia in 66 (84.6%) patients." (PMID 23497503, 2013). "Mean serum albumin was 34.5 ± 7.4 g/L, and 53.5% had hypoalbuminemia." (PMID 23521842, 2013). "Laboratory studies revealed hyperproteinemia (89.6 g/l, reference interval 54-75 g/l), hypergammaglobulinemia (31.6%, reference interval 8-18%), hypoalbuminemia (37.1%, reference interval 47-59%), and a marginal decreased albumin/globulin-ratio (0.59, reference interval 0.59-1.11)." (PMID 22463789, 2012). "Five patients had hypoalbuminemia, with a p-albumin <3.6 g/dL." (PMID 22073219, 2011). "The most common reasons to prescribe albumin were volume expansion after the heart surgery (53.3%), nutrition source in malnourished patients (19.3%), paracentesis (12.9%), plasmapheresis (9.6%), hypoalbuminemia (3%) and the others (2.1%)." (PMID 24250369, 2011). "A study evaluating serum albumin as a prognostic factor for patient survival in cancer of gastric cardia found that in each cancer stage, the 5-year survival rate of patients with normal serum albumin levels was better than that among those with hypoalbuminemia." (PMID 21176210, 2010). "Decreasing levels of renoprotective albumin might be an additional mechanism underlying the nephrotoxicity of HES, which has been shown to cause iatrogenic hypoalbuminemia." (PMID 21029460, 2010). "This may be expected, as albumin administration is generally added to resuscitative fluids in very ill patients or patients with hypoalbuminemia and/or edema." (PMID 16356223, 2005). "In addition, the most rapid disease progression was seen in patients with the most profound hypoalbuminemia (serum albumin level < 25 g/L)." (PMID 15985177, 2005). "As such, our objective was to conduct a scoping review of the literature to 1) identify albumin level cutoff values used to define hypoalbuminemia in patients with metastatic spine disease, and to 2) describe the association between serum albumin level and operative/non-operative outcomes." (PMID 40103850, 2025).